RNU4-62P (RNA, U4 small nuclear 62, pseudogene)
Gene: Small nuclear RNA gene on chromosome 3 (121,655,475 to 121,655,604, reverse strand). Ensembl gene ENSG00000222057.
Homologues: Orthologues: chimpanzee U4 (93% identical), rat LOC120098739 (58% identical), dog U4 (51% identical), dog U4 (48% identical). Paralogues in human: RNU4-13P (77% identical), RNU4-84P (74% identical), RNU4-44P (73% identical), RNU4-12P (71% identical), RNU4-68P (71% identical), RNU4-8P (70% identical), RNU4-16P (69% identical), RNU4-58P (69% identical), RNU4-7P (69% identical), RNU4-67P (68% identical), RNU4-73P (68% identical), RNU4-42P (67% identical), and 80 more.